FAM182B (family with sequence similarity 182 member B)
Gene: Long non-coding RNA gene on chromosome 20 (25,755,861 to 25,868,225, reverse strand). Ensembl gene ENSG00000175170.
Diseases named in the same sentence as FAM182B in open-access papers:
FAM182B is named in the same sentence as 5 diseases in open-access papers, as found by Europe PMC text mining. Sharing a sentence is not in itself a finding about the gene and the disease. The quoted sentences say what the papers report.
hepatocellular carcinoma (1 paper, 2022). A malignant tumor that arises from hepatocytes. "Moreover, FAM182B has been reported to be associated with hepatocellular carcinoma." (PMID 35572729, 2022).
liver cancer (1 paper, 2023). An epithelial or non-epithelial malignant neoplasm that arises from the liver. "Secondly, relevant experimental data demonstrating the relationship between the AGAP11 and FAM182B genes and the prognosis of HCC are lacking; however, the significantly related genes used in this study have been confirmed to be involved in the occurrence of liver cancer." (PMID 36726348, 2023).
cancer (1 paper, 2023). A tumor composed of atypical neoplastic, often pleomorphic cells that invade other tissues. "Similarly, there are no reports on FAM182B, a risk gene included in our model, in the field of cancer." (PMID 36726348, 2023).
FAM182B also shares sentences with these, for which no sentence is quoted: lung adenocarcinoma (1 paper); tumor (1).